IL1B (interleukin 1 beta)
Diseases named in the same sentence as IL1B in open-access papers (continued):
Sharing a sentence is not in itself a finding about the gene and the disease.
diabetes (continued). "Prior to diabetes onset, UCD‐T2DM rats had significantly higher circulating levels of IL‐6 and IL‐1β, and these elevations persisted throughout disease progression, with only CRP showing a significant increase at 8 weeks post‐onset." (PMID 42086336, 2026). "Diabetes increased IL-10, IL-17, IL-22, and TNF-α levels, and reduced IL-1β levels in the colon of diabetic mice compared to non-diabetic controls, without altering the content of IL-4, IL-6, and TGF- β1." (PMID 40496562, 2025). "Manna reported that L‐cysteine supplementation reduced NF‐κB phosphorylation and the secretion of TNF‐α, MCP‐1, IL‐8, IL‐1β, and IP‐10 by increasing AMPK phosphorylation and PPARγ expression against vascular inflammation in diabetes mediated by PI3K." (PMID 41280738, 2025). "Participants with diabetes had significantly higher hs‐CRP, IL1‐β, TNF, IL‐6 and IFG levels compared to the controls." (PMID 40525652, 2025). "ADMA is elevated in diabetes and periodontitis; higher GCF ADMA correlates with IL‐1β and clinical parameters." (PMID 41328144, 2025). "Chronic inflammation and oxidative stress are pivotal in the interplay between periodontitis and diabetes, with inflammatory cytokines such as tumor necrosis factor-alpha (TNF-α) and interleukin-1 beta (IL-1β) playing central roles in this connection." (PMID 40283848, 2025). "Biomarker Development: Further research is needed to identify and validate inflammatory biomarkers (e.g., IL-1β, TNF-α) for predicting diabetes progression and treatment response." (PMID 40218134, 2025). "Pro-inflammatory cytokines such as interleukin-1 beta (IL-1β) and tumor necrosis factor-alpha (TNF-α) play pivotal roles in the pathogenesis of diabetes by directly impairing pancreatic beta-cell function and promoting systemic metabolic dysregulation." (PMID 40218134, 2025). "In the final model with all predictors, VIF’s were the following: age = 1.22, sex = 1.04, hypertension or CVD = 1.18, diabetes = 1.26, cancer = 1.01, IL-6 = 1.27, TNFR1 = 1.99, IL-1b = 1.04, TNF-a = 1.55, IL-10 = 1.11, GDF15 = 2.16." (PMID 41280118, 2025). "Pro-inflammatory cytokines, such as interleukin-1 beta (IL-1β), tumour necrosis factor-alpha (TNF-α) and interleukin-6 (IL-6), are elevated in patients with diabetes and have been shown to alter glucose metabolism through various signalling pathways." (PMID 40227199, 2025). "The shared pathways between neuroinflammation and diabetes mellitus involve the NLRP3 inflammasome and subsequent production of the IL-1β." (PMID 40771585, 2025). "Patients with diabetes who have proliferative retinopathy show heightened levels of inflammatory mediators, such as tumor necrosis factor-alpha (TNF-α), interleukin-1 beta (IL-1β), soluble interleukin-2 receptor (sIL-2R), and interleukin-8 (IL-8)." (PMID 40332476, 2025). "The GSEA analysis further demonstrated the pivotal roles of CXCL8, IL1B, and CCL2 in diabetes through immune and inflammatory mechanisms." (PMID 38167125, 2024). "Here, we specifically detected reduced expressions of IL1β, IL6, IL10 and VEGF-A in M1/proinflammatory macrophages at the inflammatory stage in diabetes." (PMID 38270651, 2024). "In terms of SCFAs, for flaxseed oil exerted anti-diabetes action on streptozotocin-nicotinamide-induced rats, the acetic acid was negatively correlated with TNF-α, IL-1β, IL-6, and IL-17A." (PMID 39403395, 2024). "Our study showed that diabetes led to increased TNF-α, IFN-γ, and IL-1β levels, whereas intravitreal injection of porous Se@SiO2 nanospheres decreased the levels of these cytokines in db/db mice." (PMID 38321393, 2024). "Prior studies have discovered elevated amounts of inflammatory markers such as IL-1β, TNF-α, and IFN-γ, which were presented in human with diabetes, pig with malnutrition, and mice fed high-carbohydrate diets." (PMID 38668364, 2024). "Gene Set Enrichment Analysis revealed that CXCL8, IL1B, and CCL2 have significant potential in diabetes." (PMID 38167125, 2024).
diabetes (continued). "The results showed that intravitreal injection of AAV-sh-USP25 alleviated diabetes-induced retinal inflammation 8 weeks after STZ injection, as evidenced by reduced expression levels of Iba-1, MCP-1, IL-1β, and TNF-α." (PMID 38436811, 2024). "Our study investigated the expression of IL-1β, IL-10, CYP2C8, CYP2C9, CYP2J2 and sEH in HBCs from patients with type 1 diabetes mellitus (T1DM) and gestational diabetes mellitus (GDM) compared to healthy controls using immunohistochemistry." (PMID 38590527, 2024). "Elevated levels of pro-inflammatory cytokines, including IL-1β, IL-6, and TNF-α, are often observed in diabetic mellitus patients." (PMID 39050988, 2024). "In diabetes, hyperglycemia can stimulate the activation of NLRP3, thus activate Caspase-1, which can promote the maturation of cytokines pro-IL-1β and pro-IL-18 to release the cleaved fragments of active IL-1β and IL-18, and lead to pyroptosis." (PMID 39545058, 2024). "Like astaxanthin, it was found that metformin (used as a first-line therapy for type 2 diabetes mellitus) can decrease the cellular level of NF-κB which leads to decreasing the cellular levels of TNF-α, IL-1β, and IL-6." (PMID 39693313, 2024). "As almond oil displayed anti-diabetes activity in streptozotocin-induced rats, Clostridium_sensu_stricto_1 was positively correlated with FBG, MDA, TNF-α, IL-1β, and Keap1 and was negatively correlated with insulin, body weight, SOD, CAT, Nrf2, and HO-1." (PMID 39403395, 2024). "In diabetes the cytokines including interferon-γ (IFN-γ) and interleukin 1 (IL-1β) are responsible to mediate an autoimmune response by activating NF-κB which causes destruction in pancreatic β-cells." (PMID 36653816, 2023). "Diabetes augments levels of inflammatory cytokines such as TNF-α, interleukin-1β (IL-1β), interleukin-17 (IL-17), interleukin-23 (IL-23), and interleukin-6 (IL-6) in human periodontal tissue." (PMID 36875028, 2023). "Among subjects with diabetes, those with TIR ≤ 70% had higher levels of IL-1α, IL-1β, IL-6, IL-12 p70, IL-16, LIF, M-CSF, MCP-1, MCP-3, RANTES, TNF-α, TNF-β, and b-NGF, and lower levels of IL-1α, IL-4, IL-10, GM-CSF, and MIF than individuals with TIR > 70%." (PMID 37893217, 2023). "In this issue, we discussed how the residual aqueous fraction of E. conyzoides has modulatory potential against some of the metabolite derangements seen in diabetes, including elevated levels of oxidative stress marker (MDA), IL-1β and TNF-α." (PMID 37065804, 2023). "In addition, it is worth mentioning that researchers have recognized the relationship between IL-18 and IL-1β secretion, which significantly increases the expression of IL-1β, suggesting that IL-18 may promote the development of diabetes through its interaction with IL-1β." (PMID 37868953, 2023). "Prior reports demonstrating STING-enhanced senescence in chondrocytes exposed to IL-1β and HG-induced increased β-galactosidase activity in cultured endothelial cells support a role for STING in REC senescence in diabetes." (PMID 37345657, 2023). "Long-term hyperglycemia is a major feature of diabetes, which induces the inflammatory response by activating the NLRP3 inflammasome to promote the production of interleukin (IL)-1β." (PMID 38127000, 2023). "Our data demonstrated that the serum proinflammatory cytokines IL-1β, TNF-α, IL-2, IFN-γ, and IL-4 and the anti-inflammatory cytokine IL-10 were dysregulated in diabetes and improved by OI intervention." (PMID 36918798, 2023). "The overexpression of cytokines IL-1β, IL-6, and TNF-α is known to affect systemic acute inflammatory syndrome, chronic immune disease, pain, cardiovascular disease, and diabetes." (PMID 37764215, 2023). "Metformin, as a well-known drug for diabetes, can inhibit SASP by decreasing the expression of IL-1β, IL-6, C-X-C motif chemokine 5 (CXCL5) and NF-kB." (PMID 36744145, 2023).
diabetes (continued). "Protein lysates of individual retinas (n = 9/group) were collected for automated Ella quantification of IL-1β, IL-6, and TNF-α; 2 months after diabetes was confirmed." (PMID 36674854, 2023). "Many studies have demonstrated that diabetes can increase the levels of human pro-inflammatory factors, such as TNF-α, IL-1β, and IL-6." (PMID 35813617, 2022). "The role of pro-inflammatory cytokines, such as IL-1β and TNF-α, in the mediation of chronic inflammation and disruption of the BRB has been well documented in several animal models of diabetes and DR." (PMID 36139465, 2022). "A report has indicated that the overexpression of miR-342-3p following inhibition of NEAT1 decreases the release of the inflammatory cytokines IL-6, IL-1β, TNF-α, and cyclooxygenase-2 in type 1 diabetes mellitus." (PMID 36310619, 2022). "In line with this, the proinflammatory cytokines, IL1B and IL6 were downregulated on the mRNA level in urine exfoliated cells from patients with diabetes." (PMID 36127330, 2022). "Diabetes induced the upregulation of serum TNF-α, IL-6, and IL-1β, and treatment with anti-ANGPTL3/IL22 showed prominent reversal compared with mIL22Fc or anti-ANGPTL3 alone." (PMID 36544775, 2022). "Diabetes also inhibits the proliferation and differentiation of osteoblasts in alveolar bone by activating the caspase-1/GSDMD/IL-1β pathway." (PMID 36093182, 2022). "Previous studies have revealed that HMGB1 inhibitor GA treatment protects against kidney lesions induced by diabetes, which is related to the reduced expression of TNF-α, 1L-6, IL-1β, MCP-1, and ICAM-1 in the kidney." (PMID 35578754, 2022). "Rather, sustained STING expression in diabetes is detrimental to wound healing due to decreased Mφ-mediated IFN-I production and increased IL-1β, TNF-α, and IL-6 production, all of which act in concert to sustain a proinflammatory Mφ phenotype." (PMID 36127466, 2022). "Diabetes triggered NLRP3, ASC, gasdermin-N, caspase-1, and collagen I expression in myocardial tissue, and promoted an increase in the serum TNF-α, IL-1β, IL-6, and IL-18 levels." (PMID 36320147, 2022). "Previous reports indicated that persistent hyperglycemia was closely associated with a pro-inflammatory status, characterised by a significant elevation of IL-1β, IL-6, -1B and -8 and TNF-α in patients with uncontrolled diabetes and ketoacidosis." (PMID 35327652, 2022). "Several pro-inflammatory markers, such as C-reactive protein, IL-1b, IL-6, IL-8, and TNF-α, are elevated in migraine and diabetes." (PMID 36498528, 2022). "Diabetes induction resulted in an increase in proinflammatory parameters TNF-α, IL-1β and IL-6, which were estimated using an ELISA technique in this study." (PMID 35335923, 2022). "Diabetes resulted in an increase in NLRP3 content in atrial tissue, a rise in the serum IL-1β and IL-18 concentrations." (PMID 36320147, 2022). "Similarly, in a “diabetes-like” condition, the phosphomimetic (148D) HspB4/αA-crystallin mutant had an even greater dampening effect than that of the WT HspB4/αA-crystallin as demonstrated by a greater decrease in the induction of IL-6 (78%), IL-1β (79%), and MCP-1 (83%)." (PMID 34071438, 2021). "In a diabetes animal model, the proinflammatory cytokines IL-6, TNF-α, and IL-1β increased significantly in rat pancreatic tissue." (PMID 33774704, 2021). "Chronic and progressive inflammation indicated by elevated hippocampal IL‐1β and TNF‐α expression is known to play a role in diabetes‐related dementia." (PMID 33346402, 2021). "Various studies have reported that increased expression of inflammatory markers such as IL-6, IL-1β, and MCP-1 inactivated retinal MGCs due to diabetes-induced stress." (PMID 34071438, 2021). "The activation of diabetes-mediated related factors such as TLR4, NLRP3, caspase-1, IL-1β, IL-18, and GSDMD-NT plays a vital role in the pathophysiology of DKD." (PMID 33692782, 2021).
diabetes (continued). "Evidence has shown that the NLRP3 inflammasome, IL-1β, thioredoxin-interacting protein (TXNIP), and pyroptosis play vital roles in the development of diabetes." (PMID 34356130, 2021). "Our results in mice are consistent with the study of a streptozotocin-induced diabetes rat model, wherein increased levels of the proinflammatory cytokines IL-6, TNF-α, and IL-1β were found in diabetic rat pancreatic tissue." (PMID 33774704, 2021). "Studies have indicated that various pathological factors such as diabetes, osteoarthritis, and IDD induce cellular senescence, apoptosis, inflammatory response, and oxidative stress via IL-1β." (PMID 34926442, 2021). "Addition of IL-1β stimulated the expression of MMPs and inhibited the production of TIMPs and collagenase suggesting that IL-1β promotes ECM degradation and delays the process of wound healing in diabetes." (PMID 34054346, 2021). "Changes in diabetes-related inflammatory status were measured in terms of IL-6, TNF-α, and IL-1β levels in the serum and phospho NFκB-p65 protein expression." (PMID 34439476, 2021). "In this current study, we determined that administering one weekly 100 μL subcutaneous injection of saline containing 20 μM of XMD8-92 was sufficient to ameliorate diabetes-mediated IL-6 and VEGF production, and significantly decreased IL-1β in diabetic mice." (PMID 34456740, 2021). "In the CANTOS study (Canakinumab Anti-inflammatory Thrombosis Outcome Study), the blockade of IL-1β with canakinumab diminished inflammatory markers (hsCRP and IL-6) and the cardiovascular risk in atherosclerosis patients, but did not reduce the incidence of diabetes." (PMID 32471207, 2020). "In our study, we found that increased Blautia was positively correlated with inflammatory indicators (IL-1β, TNF-α, IL-6 and LPS) in diabetes." (PMID 32028957, 2020). "In a model of streptozotocin-induced diabetes in Sprague–Dawley rats, bFGF delayed the progression of diabetic nephropathy, possibly by inhibiting NF-κB and silencing of TGF-β1, MCP-1, IL-6, and IL-1β." (PMID 32961903, 2020). "It is evident that monocytes isolated from obese humans with diabetes display an inflammatory phenotype and secrete higher levels of pro-inflammatory mediators such as IL-6, MCP-1, and IL-1β leading in metabolic dysfunction." (PMID 33033337, 2020). "In this case report, we described for the first time the differential expression of TNF-α, IL-1β, IL-6, and IFN-γ in a blood sample that was taken from a 27-year-old patient with type 1 diabetes mellitus (T1DM) who was diagnosed with HU." (PMID 33375551, 2020). "To investigate the role of Ufm1 in diabetes mice, we first analyzed the expression of Ufm1 and proinflammation cytokines (TNF-α, IL-6, and IL-1β) in db/db mice." (PMID 31829413, 2020). "We extended these data, demonstrating that HG increases the gene expression and secreted form of IL-1β and MCP-1 in both VEC and VIC, in a 3D model of aortic valve leaflet, indicating that these molecules might have an important role in chronic inflammation associated with CAVD in diabetes." (PMID 33255639, 2020). "For example, cytokines such as interferon gamma (IFNɣ), interleukin 1 beta (IL1β) and tumor necrosis factor alpha (TNFα; also known as TNF) can drive beta (β) cell dysfunction, damage and death in diabetes mellitus." (PMID 32457041, 2020). "In our results, positive correlations of Firmicutes with pro-inflammatory IL-1β, TNF-α, IL-6, IL-17A and LPS demonstrated that both pro-inflammatory indicators and Firmicutes contributed to pathogenesis of diabetes." (PMID 32028957, 2020). "Neurological degeneration was also significantly improved, accompanied by decreased levels of inflammatory factors (TNF‐α, 57.8%; IL‐1β, 51.4%; IL‐6, 62.8%; and MDA, 40.7% reduction rate against the diabetes mellitus + normal saline group)." (PMID 33215875, 2020). "Eight weeks CS or metformin administration decreased IL-1β, IL-6 and TNF-α levels (CS vs. diabetes, p < 0.01, Met vs. diabetes, p < 0.01)." (PMID 32722636, 2020).
diabetes (continued). "In diabetes, PLEK has been reported to promote the secretion of proinflammatory cytokines such as TNF-α and IL-1β in mononuclear phagocytes; these cytokines have already been linked to increased risk of UC and RA." (PMID 33262784, 2020). "From in vivo studies, osthole (20 mg/kg per day for 14 days) reduced the up-regulation of the P2X4 receptor, and downregulated the IL-1β, TNF-α, brain-derived neurotrophic factor, and p-p38MAPK and upregulated IL-10 in diabetes mellitus." (PMID 32028721, 2020). "Many studies have shown that proinflammatory cytokines including TNF-α, IL-6, IL-1β, CRP, and NF-κB can lead to IR and the development of related diseases such as metabolic syndrome and diabetes, either alone or in combination, via various pathways." (PMID 31218568, 2019). "The evidence has shown that the NLRP3 inflammasome, IL-1β, thioredoxin-interacting protein (TXNIP), and pyroptosis play vital roles in the development of diabetes." (PMID 31835423, 2019). "In the present study, induction of diabetes increased (p < 0.05) levels of proinflammatory cytokines TNF-a, IL-1b and IL-6 in rats." (PMID 31412679, 2019). "Our results indicate that diabetes increases the levels of NFκB, NLRP3 inflammasome, and IL-1β in the hippocampus, suggesting that activation of diabetes-induced NLRP3 and enhanced secretion of IL-1β contribute to the progression of diabetic encephalopathy." (PMID 30911292, 2019). "Present study showed that pro-inflammatory markers i.e., TNF-α, IL-1β, and IL-6 together induce chronic inflammation condition to promote CAD in diabetes." (PMID 30674322, 2019). "With diabetes, NLRP3 is stimulated by the ER stress and cleaves and stimulates caspase-1, leading to secretion and release of the pro-inflammatory cytokines IL-1β and IL-18." (PMID 30657794, 2019). "To further confirm the in vitro suppressive effect of glucocorticoids on IL‐1β‐induced galectin‐1/LGALS1 expression, we used the in vivo model of STZ‐induced diabetes in mice." (PMID 31328390, 2019). "In contrast, in patients with diabetes who had poorly controlled blood glucose levels, TNF-α, IFN-γ, IL-2, and IL-1β cytokine levels were increased in response to PPD." (PMID 31815150, 2019). "Regarding the mechanisms involved in the beneficial effect of the SOCS1 peptidomimetic, we found that it reduces the upregulation of IL-1β, IL-6, TNF-α, and VEGF induced by diabetes." (PMID 31344857, 2019). "In this study, IL-1β levels increased significantly in the STZ-induced group of animals when compared to the normal Group 1, which represented the induction of diabetes and hepatic injury." (PMID 30937278, 2019). "Another research group reported similar effects in an in vivo study on diabetes; in the hippocampi of STZ mice, the expression of IL-1β is greater than that in the controls, and metformin reduces this effect." (PMID 31197747, 2019). "Diabetes increased the retinal levels of TNF and IL-1β, but the treatment with SCH 58261 only slightly attenuated the expression of TNF." (PMID 31748653, 2019). "The intraperitoneal administration of GNF-2 significantly decreased the diabetes-induced increase in the expression of pro-inflammatory cytokines such as TNF-α and IL-1β mRNAs in the spinal cord tissues." (PMID 31164822, 2019). "The healing properties of NT have been confirmed in a murine model of diabetes, where collagen matrices, loaded with NT-enhanced wound healing, decreased the expression of TNF-α and IL-1β and reduced the infiltration of inflammatory cells into the wound." (PMID 31614422, 2019). "The results of the findings indicate that diabetes mediates testicular damage by increasing the expression of NF-κB which elicit inflammatory cytokine activities, such as those of IL-6, TNF-α, and IL-1β, to promote inflammatory responses." (PMID 31583254, 2019).